TBP (TATA-box binding protein)
Diseases named in the same sentence as TBP in open-access papers (continued):
Sharing a sentence is not in itself a finding about the gene and the disease.
tumor (34 papers, 2002 to 2025). "We then performed qRT-PCR for RD3 expression in the GBM tissues from the Evangelisches Krankenhaus cohort and found a significant downregulation of RD3 expression in GBM compared to non-tumor tissue (expression normalized to TBP and HPRT1)." (PMID 40234400, 2025). "ADAR1 knockdown in both tetraploid-sorted and diploid-sorted TBP ARPE cells delayed tumor growth, taking on average 35 weeks and 33 weeks, respectively, to reach the maximum size." (PMID 39189458, 2024). "It has been reported that transcription factor TBP stimulates RNA synthesis to promote tumor cell proliferation." (PMID 37020316, 2023). "An increasing body of evidence suggests that TLP (TBP-2), a family member of TBP, is a tumor suppressor gene that plays a key role in DC-induced T-cell responses." (PMID 35969172, 2022). "Hierarchical clustering analysis including oviductal WT organoids, TBP mutants, and the six independent oviductal TBP clone-derived tumors assigned the organoids and the tumor tissues into two separate clusters." (PMID 32461556, 2020). "Using an adequate number of cases to provide sufficient statistical power, we found significant enrichment of TBP mRNA in tumor-derived epithelium compared to matched normal colon epithelium." (PMID 28415573, 2017). "Collectively, these studies support a new role for TBP in promoting tumor vascularization through its ability to modulate VEGFA expression." (PMID 28415573, 2017). "In order to identify TBP-mediated changes in gene expression that drive tumor formation, we conducted a microarray analysis to compare changes in gene expression in R1A cells that expressed increased amounts of TBP (R1a-hTBP) to vector control cells." (PMID 28415573, 2017). "As previous studies demonstrated that increases in cellular TBP concentrations can promote tumor formation in athymic mice, we sought to understand how this increase in TBP drives this process." (PMID 28415573, 2017). "Previously, we showed that small increases in TBP protein expression (∼20%) in Rat1a (R1a) cells was sufficient to induce tumor formation in athymic mice." (PMID 28415573, 2017). "Depletion of NRP2 in TBP tumour cells using shRNA significantly attenuated their ability to form tumours in mice." (PMID 23436775, 2013). "The analysis showed nearly parallel expression to whole-tissue from the same tumor using the 4-group reference genes for ER+ IBC of TBP, RPLP0, PUM1 and ACTB, as observed by a Pearson correlation of 0.992." (PMID 18211679, 2008). "Given the enrichment and consistent increase in TBP-mediated changes of expression for genes that regulate angiogenesis, we assessed whether enhanced TBP expression might support tumor growth by enhancing tumor vascularization." (PMID 28415573, 2017). "Comparing relative tumor TBP expression and the tumor stage or Duke's index did not reveal any association between increased tumor TBP expression and these factors (data not shown)." (PMID 28415573, 2017). "Besides interacting with TCF/LEF, β-catenin also binds to p300/CBP, TATA-box binding protein (TBP), Pontin52, Reptin52, Brg-1, MUC1-C, SOX10, p68/p72, FOXM1, yes-associated protein 1 (YAP1) and FBW1, which are all involved in tumor development or progression." (PMID 28430641, 2017). "Cells derived from TBP tumours form mammospheres that are dependent upon NRP2." (PMID 23436775, 2013). "The FC in gene expression of each marker in tumour samples relative to healthy controls was determined using the 2− ΔΔCt method normalised to the average of 7 housekeeping genes (YWHAZ, CYC1, SDHA, TBP, GAPDH, UBC and 18s RNA)." (PMID 41034696, 2025). "TEAD4, TBP, MYC, and ELF5 constituted the transcription factor regulatory network of C2 CPE+ tumor cells." (PMID 40230840, 2025). "METTL16 overexpression significantly inhibited tumor growth and metastasis (P<0.001) by downregulating CAPN2 through an indirect mechanism involving the transcription factor TBP and the gene MROH8." (PMID 39434688, 2024).
tumor (continued). "The low molecular weight D-peptide TBP-3 that targets TIGIT was reported to penetrate and accumulate in the tumor tissues." (PMID 37129788, 2023). "In this study, a novel D-peptide TBP-3, was conjugated with 68 Ga to non-invasively detect TIGIT expression in tumor-bearing BALB/c mice." (PMID 37129788, 2023). "Five genes at 6q27 exhibiting large genomic changes (PSMB1, PDCD2, TBP, OR4F7P and WBP1LP8) were found in HCI-010 as the region transitioned from amplified in the human tumor to deleted in the early passage of the PDX and PDxO." (PMID 35221336, 2022). "Our studies identify a new molecular node that connects growth factor signaling, TBP, and VEGFA expression to promote tumor development." (PMID 28415573, 2017). "Increased TBP expression induces VEGFA expression and enhances cell migration and tumor vascularization." (PMID 28415573, 2017). "In order to evaluate and screen the optimal endogenous control for lncRNAs analysis of tissues and cells, the candidate reference genes (GAPDH, TBP, β-actin and HPRT1) were measured in 21-pair ESCC tumor tissues and adjacent normal tissues." (PMID 25608466, 2015). "Among malignant samples, the expression of reference genes was substantially equivalent among tumor grade groups for ACTB, PPIA and TBP." (PMID 25473950, 2014). "Expression of IPO8, RPL4, TBP, RPLPO, and ACTB had the least variation in expression across the tumour samples according to GeNorm, NormFinder, and BestKeeper." (PMID 24001041, 2013). "The expression of IL-FABP in normal and tumour tissues were normalised against the geometric mean expression of the two reference genes PPIA and TBP." (PMID 21767383, 2011). "The expressions of B- and L-FABP in normal and tumor tissues were normalized against the geometric mean expression of the two reference genes PPIA and TBP." (PMID 19622156, 2009). "TBP's ability to induce VEGFA production and the importance of VEGFA in driving tumor growth prompted us to investigate whether TBP expression is elevated in human tumors relative to normal tissue." (PMID 28415573, 2017). "While our analysis also revealed that there are other angiogenesis-enriched TBP-regulated genes that could conceivably contribute to the ability of TBP to regulate cell migration and tumorigenesis, changes in VEGF, alone, can drive tumor angiogenesis." (PMID 28415573, 2017). "Furthermore, expression of pY397 FAK is markedly elevated in TBP transgenic tumours compared to MMTV-PyV-MT tumours, and the α6high/NRP2high population sorted from TBP tumour cells exhibited markedly higher FAK activation than did the α6low/NRP2low population." (PMID 23436775, 2013). "Organs from an egg without a tumor were used to test eight primers for cross‐reactivity with the chicken cells, namely B2M, HMBS, ALTB, TBP, SDHA, YWHAZ, and UBC." (PMID 40443053, 2025). "These four genes were consequently excluded from geNorm analysis and the three candidate controls whose expression levels did not significantly vary between normal and tumor tissues (HMBS, HPRT1 and TBP) were reevaluated by the geNorm software." (PMID 19257903, 2009). "To test this hypothesis, we injected diploid- and tetraploid-sorted TBP ARPE cells with or without stable ADAR1 knockdown under the skin of immune-compromised NMRI mice, which lack T-cells, and monitored tumor outgrowth over time." (PMID 39189458, 2024).
infection (19 papers, 2011 to 2025). The state of being infected such as from the introduction of a foreign agent such as serum, vaccine, antigenic substance or organism. "Using chromatin immunoprecipitation sequencing (ChIP-seq), we analyzed the association of modified histones, TBP, and Pol II with the early viral promoters after infection with wild-type (wt) and Ad5 mutants." (PMID 29976669, 2018). "As was seen for the endogenous protein, wild-type MEF2.HA associated with endogenous TBP only after infection." (PMID 24075010, 2013). "In a separate DFF ChIP-Seq experiment comparing HFF and D-NT2 infections at 96 h pi, the histone H3.3 variant and H3K4me3 were found to co-occupy the MIEP but their levels relative to TBP at the MIEP were lower in HFF compared to D-NT2." (PMID 40758707, 2025). "Chromatin immunoprecipitation (ChIP) studies further showed that blast infection triggers rapid recruitment of TBP and RNA polymerase II to TATA-containing defense gene promoters, peaking within 2–4 h post-inoculation." (PMID 41300312, 2025). "In healthy animals, MEF2 is phosphorylated at T20 and promotes expression of its metabolic targets, whereas infection results in T20 dephosphorylation and association with the TATA-binding protein (TBP) at a distinct TATA sequence of immune targets." (PMID 24075010, 2013). "Cytochrome P450-like TBP (TATA box binding protein) showed a significant early response at 3 hr after infection with P. cinnamomi reacting with an increase of ten-fold." (PMID 22108245, 2011). "Nonphosphorylatable MEF2 associated with TBP even in the absence of infection; this association was strengthened by infection, suggesting that other MEF2 or TBP modifications also contribute to complex formation." (PMID 24075010, 2013). "Next, we investigated whether changes in Pol III transcription induced by infection were associated with changes in the chromatin structure around Pol III-transcribed genes, once more drawing upon our recently published DFF-ChIP data for H3K4me3 and TBP." (PMID 35458509, 2022). "The virtual absence of H3K18/27ac at the E2early promoter following infection with the DM correlated with an absence of TBP and Pol II association, suggesting that H3K18/27ac by p300/CBP is required for E1A stimulation of Pol II preinitiation complex assembly in vivo at this promoter." (PMID 29976669, 2018). "For example, in the M1T3DS[T3DK] infection, the modulation of ABI1 and TBP ASE is respectively increased and decreased as compared to WT T3DS." (PMID 35489070, 2022). "Due to the attenuated infection, HSV-1 induced host shutoff, as measured by RNA levels of the housekeeping genes POLR1B, SDHA, TBP, and PPIA, which were reduced." (PMID 29089033, 2017). "At later times (14–24 h) after infection, IRF7 and TBP are released from the promoter, concomitant with histone H3K9 and H3K14 deacetylation; the attenuation of IFN-A gene transcription." (PMID 22685561, 2012). "At 48 h post-infection (pi) of fibroblasts, shortly after onset of HCMV replication, DFF-ChIP Seq analysis revealed structural distinctions between the viral LTF complex and host TATA-binding protein pre-initiation complex (TBP PIC) on viral genomes." (PMID 40758707, 2025). "To investigate whether this structure changes later in HFF infection or differs in D-NT2 infection, we applied the DFF-ChIP method to assess TBP and H3K4me3 histone occupancy of HCMV genomes in HFF vs D-NT2 at 96 h pi." (PMID 40758707, 2025). "In this study, BLL and infection history varied between seasons in MBP and TBP." (PMID 37508115, 2023). "ChIP analysis of these cells and wild-type (wt) U2OS demonstrated increased association of RNA polymerase II, TATA binding protein (TBP) and Oct1 transcription factors with viral promoters in the absence of IFI16 at different times post infection." (PMID 25375629, 2014).
infection (continued). "Additionally, EnAd infection led to the up- and down-regulation of host genes not directly related to the HIF-pathway such as Proliferating Cell Nuclear Antigen (PCNA) and TATA-box Binding Protein (TBP) in both hypoxic and normoxic cultures, respectively (Figure A3C)." (PMID 32244697, 2020).
neurodegenerative disease (12 papers, 2007 to 2025). A disorder of the central nervous system characterized by gradual and progressive loss of neural tissue and neurologic function. "We also observe neurodegenerative phenotypes when TBP is expressed specifically in fly eyes, a long-used genetic platform for understanding proteotoxic neurodegenerative diseases." (PMID 37551423, 2023). "Evidence implicating TBP in the molecular mechanism of several neurodegenerative diseases has emerged in the past few years." (PMID 36561136, 2022). "Brain sections of patients with spinocerebellar ataxia 17 (SCA17), a type of neurodegenerative disease, have been reported to contain protein aggregates of TATA-binding protein (TBP)." (PMID 28774347, 2017).
neurological disorders (8 papers, 2016 to 2025). "We considered four loci implicated in neurological disorders resulting from pathogenic expansion of a trinucleotide repeat and uncovered evidence for selection at one: the microsatellite in TATA-box binding protein (TBP)." (PMID 39775235, 2024). "TBP (TATA-binding protein) plays a critical role in the formation of transcription initiation complex, and its aberrant expression may induce neurological disorders." (PMID 38950180, 2024).
metabolic disease (3 papers, 2020 to 2025). A congenital disorder (due to inherited enzyme abnormality) or acquired (due to failure of a metabolically important organ) disorder resulting from an abnormal metabolic process. "TBP and ATPF1 should be used as reference genes in qPCR experiments on the adipose tissue with metabolic disease." (PMID 33330591, 2020).
autosomal dominant inherited disorder (1 paper, 2023). "SCA17 is largely an autosomal dominant inherited disorder, but de novo TBP mutations have also been reported in patients." (PMID 37551423, 2023).
blood disorders (1 paper, 2020). "Atherogenesis-related candidate SNP markers within the gene promoters where SNPs of TBP-sites are clinically linked with blood disorders." (PMID 32033288, 2020).
brain disorder (1 paper, 2024). A disease affecting the brain or part of the brain. "As enhancer variations are being increasingly recognized as a cause of brain disorders, screening the enhancers of ATXN1, ATXN3, TBP and ITPR1 for variations other than CNVs and identifying and screening enhancers of other SCA genes might elucidate the genetic cause in undiagnosed patients." (PMID 39456985, 2024).
cardiovascular diseases (1 paper, 2020). "Atherogenesis-related candidate SNP markers within the gene promoters where SNPs of TBP-sites are clinically linked with cardiovascular diseases." (PMID 32033288, 2020).
TBP also shares sentences with these, for which no sentence is quoted: spinobulbar muscular atrophy (8 papers); movement disorder (6); cerebellar ataxia (4); dementia (4); Intellectual disability (4); amyotrophic lateral sclerosis (3); spinocerebellar ataxia type 1 (3); acute myeloid leukemia (2); Adult onset (2); fragile X syndrome (2); frontotemporal dementia (2); hepatocellular carcinoma (2); Huntington disease-like 2 (2); lupus (2); microcephaly (2); myotonic dystrophy type 1 (2); neurodevelopmental disorder (2); osteosarcoma (2); Ovarian Tumors (2); renal cell carcinoma (2); sarcoma (2); schizophrenia (2); Spastic paraplegia (2); adenocarcinoma (1); adrenocortical carcinoma (1); Anxiety (1); ataxia telangiectasia (1); bacterial infections (1); benign hereditary chorea (1); cerebellofaciodental syndrome (1).
A further 37 diseases each share a sentence with TBP in 1 paper.